COX6A2 (cytochrome c oxidase subunit 6A2)
Description:
Component of the cytochrome c oxidase, the last enzyme in the mitochondrial electron transport chain which drives oxidative phosphorylation. The respiratory chain contains 3 multisubunit complexes succinate dehydrogenase (complex II, CII), ubiquinol-cytochrome c oxidoreductase (cytochrome b-c1 complex, complex III, CIII) and cytochrome c oxidase (complex IV, CIV), that cooperate to transfer electrons derived from NADH and succinate to molecular oxygen, creating an electrochemical gradient over the inner membrane that drives transmembrane transport and the ATP synthase. Cytochrome c oxidase is the component of the respiratory chain that catalyzes the reduction of oxygen to water. Electrons originating from reduced cytochrome c in the intermembrane space (IMS) are transferred via the dinuclear copper A center (CU(A)) of subunit 2 and heme A of subunit 1 to the active site in subunit 1, a binuclear center (BNC) formed by heme A3 and copper B (CU(B)). The BNC reduces molecular oxygen to 2 water molecules unsing 4 electrons from cytochrome c in the IMS and 4 protons from the mitochondrial matrix. Plays a role in the assembly and stabilization of complex IV.
Synonyms: COXVIAH; COX6AH; COXVIa-M; MC4DN18
Tractability: Antibody: UniProt predicts a signal peptide or a membrane-spanning region.
Gene: Protein-coding gene on chromosome 16 (31,427,731 to 31,428,360, reverse strand). Ensembl gene ENSG00000156885.
Subcellular location: Mitochondrion inner membrane
Pathways (Reactome):
Metabolism: Complex IV assembly; Respiratory electron transport
Cellular responses to stimuli: Cytoprotection by HMOX1
Gene Ontology:
Molecular function: enzyme regulator activity
Biological process: generation of precursor metabolites and energy; mitochondrial electron transport, cytochrome c to oxygen; oxidative phosphorylation
Cellular component: mitochondrion; mitochondrial inner membrane; respiratory chain complex IV
Genetic constraint (gnomAD): Loss-of-function variants: 8 observed, 5.77 expected, observed/expected ratio (o/e) 1.39, 90% interval 0.78 to 1.91. That is too few expected variants to judge how well the gene tolerates losing a copy. Missense variants: 174 observed, 99.44 expected, observed/expected ratio (o/e) 1.75, 90% interval 1.54 to 1.94. Synonymous variants: 63 observed, 38.01 expected, observed/expected ratio (o/e) 1.66, 90% interval 1.35 to 1.93.
Gene-disease validity (ClinGen):
ClinGen rates the evidence that COX6A2 causes each of these diseases.
mitochondrial disease (autosomal recessive): Moderate.
Homologues: Orthologues: chimpanzee COX6A2 (100% identical), macaque COX6A2 (93% identical), pig COX6A2 (84% identical), dog COX6A2 (81% identical), guinea pig COX6A2 (78% identical), mouse Cox6a2 (78% identical), rat Cox6a2 (77% identical), zebrafish cox6a1 (58% identical), tropical clawed frog cox6a1 (57% identical), Drosophila melanogaster levy (46% identical), Drosophila melanogaster COX6AL (42% identical), Drosophila melanogaster COX6AL2 (36% identical), and 1 more. Paralogues in human: COX6A1 (62% identical).
Diseases named in the same sentence as COX6A2 in open-access papers:
COX6A2 is named in the same sentence as 33 diseases in open-access papers, as found by Europe PMC text mining. Sharing a sentence is not in itself a finding about the gene and the disease. The quoted sentences say what the papers report.
Insulin resistance (5 papers, 2013 to 2024). Increased resistance towards insulin, that is, diminished effectiveness of insulin in reducing blood glucose levels. "It has been reported that COX6A2 deficient in mice protects against high-fat-diet-induced insulin resistance and obesity." (PMID 39702527, 2024). "Deficiency of Cox6a2 in mice has shown protection against insulin resistance and obesity induced by high-fat diets." (PMID 39702527, 2024). "In this study, we show that Cox6a2-deficient mice are protected against high-fat diet-induced obesity, insulin resistance and glucose intolerance." (PMID 23460811, 2013). "In addition, Cox6a2 is a respiratory chain gene, and studies have shown that Cox6a2-deficient mice can be protected from high-fat diet-induced obesity, insulin resistance, and glucose intolerance." (PMID 39096856, 2024). "A COX6A2 gene knockout mouse model exhibited diastolic cardiac dysfunction when the cardiac load was increased, showed a protective effect on insulin resistance, and COX6A2 protected neurons from oxidative stress." (PMID 38072986, 2023). "Our data indicate that COX6A2 is a regulator of respiratory uncoupling in muscle and we demonstrate that a novel and direct link exists between muscle respiratory chain activity and diet-induced obesity/insulin resistance." (PMID 23460811, 2013). "COX6A2 has an important role in thermogenesis and whole-body energy metabolism and maybe a potential new target for therapy against high-fat diet-induced obesity or insulin resistance." (PMID 32699629, 2020). "Therefore, we believe that COX6A2 may be a potential new target for therapy against obesity and/or insulin resistance." (PMID 23460811, 2013).
psychosis (4 papers, 2022 to 2024). "In the blood of early psychosis patients, oxidative stress causes the up-regulation of the miR-137, resulting in decreased cytochrome c oxidase subunit 6A2 (COX6A2) and the accumulation of impaired mitochondria." (PMID 39125827, 2024). "Similar alterations of miR-137, COX6A2, and mitophagy markers were identified in plasma of early psychosis patients." (PMID 34759358, 2022). "Oxidative stress in early psychosis patients (EPP) led to an increase in blood levels of the EV-derived miR-137 and a decrease in the cytochrome c oxidase subunit 6A2 (COX6A2) and changed mitophagy markers." (PMID 36302978, 2023).
diabetes (3 papers, 2013 to 2024). "Intriguingly, most of the identified genes, which showed strong signals in normal islets but were potently suppressed by STZ, were previously linked with important β-cell functions or diabetes development, such as Slc2a2, Ucn3, Gad1, Cox6a2, Trpm6 and Vdr." (PMID 23828045, 2013). "Based on our findings, we present the first evidence that COX6A2 promotes β-cell apoptosis in diabetes." (PMID 39702527, 2024). "For example, G6pc2, Pfkfb2, Ogdh1 and Cox6a2 were significantly affected by 4 weeks of diabetes but were unchanged by 24 h of hyperglycaemia." (PMID 27882918, 2016). "To determine whether COX6A2 is involved in β-cell apoptosis in diabetes, we investigated the protein expression of COX6A2 in islets in diabetic situations." (PMID 39702527, 2024). "This rise in COX6A2 expression might result from the reduced expression of FXR in diabetes." (PMID 39702527, 2024).
cardiomyopathies (2 papers, 2022 to 2025). "Deficiencies in COX6A2 have been linked to significant cardiac tissue remodeling and various cardiomyopathies including bradycardia." (PMID 40565507, 2025).
osteosarcoma (2 papers, 2024). A usually aggressive malignant bone-forming mesenchymal neoplasm, predominantly affecting adolescents and young adults. "In this research, five oxidative phosphorylation genes linked to the prognosis of individuals with osteosarcoma were screened out, including ATP6V0D1, LHPP, COX6A2, MTHFD2, and NDUFB9." (PMID 38506898, 2024). "COX6A2 was reported to be incorporated into the oxidative phosphorylation gene model of osteosarcoma for predicting the prognosis of patients and the infiltration of immune cells." (PMID 39569192, 2024). "Among them, COX6A2, MTHFD2, and NDUFB9 were positively correlated with risk scores, suggesting that they were risk genes for unfavorable prognosis among individuals with osteosarcoma." (PMID 38506898, 2024). "Multivariate Cox regression analysis confirmed that these 8 identified genes, including 2 protective elements (SQOR and PFKFB2) and 6 hazardous factors (MAFF, COL5A2, FAM162A, UQCRB, SFXN4, and COX6A2), could independently predict the overall survival of osteosarcoma samples." (PMID 39569192, 2024). "According to the Kaplan-Meier (KM) survival analysis of 8 modeled genes, elevated expression levels of COL5A2, COX6A2, UQCRB, SFXN4, FAM162A and MAFF sharply shortened the survival time of osteosarcoma patients." (PMID 39569192, 2024). "There are also no relevant studies on COX6A2 and the prognosis of osteosarcoma." (PMID 38506898, 2024).
Parkinson disease (2 papers, 2020 to 2022). A progressive degenerative disorder of the central nervous system characterized by loss of dopamine producing neurons in the substantia nigra and the presence of Lewy bodies in the substantia nigra and locus coeruleus. "There were three proteins included COX7B, COX6A2, and UQCRQ associated with the following pathways: oxidative phosphorylation (P = 0.003), cardiac muscle contraction (P = 0.047), Alzheimer's disease (P = 0.042), and Parkinson's disease (P = 0.028)." (PMID 33247215, 2020). "Among the proteins involved in the Alzheimer's disease and Parkinson's disease pathways, in addition to the fact that we already know that COX7B, COX6A2 and UQCRQ affect the function of mitochondria, downregulation of CASP9 is thought to lead to neurodegenerative diseases." (PMID 33247215, 2020).
schizophrenia (2 papers, 2022 to 2023). A major psychotic disorder characterized by abnormalities in the perception or expression of reality. "Consequently, inhibition of miRNA-137 in the cortex of Gclm-KO mice reversed the alterations in PV network and the decrease in COX6A2, indicative for an involvement of the miRNA-137/COX6A2 pathway in cortical PV IN circuit impairments typically observed in schizophrenia." (PMID 37213213, 2023).
acute myocardial infarction (1 paper, 2024). Necrosis of the myocardium, as a result of interruption of the blood supply to the area. "Twice the normal levels of Mb were recently associated with early acute myocardial infarction; Slc25a4 is included in the DIA pathway and Cox6a2 is included in the CMC, OXP, and DIA pathways." (PMID 38534766, 2024).
cardiac hypertrophy (1 paper, 2023). "This further verified that the COX6A2-KO myocardial cell size significantly increased, presenting hypertrophy myocardial morphology." (PMID 38072986, 2023). "Using qPCR, we found that the expression of ANP, BNP, COL1A1, and COL4A1 mRNA in cardiomyocytes following COX6A2 knockdown was significantly increased compared with that of the WT cells, suggesting that the cardiomyocytes developed toward cardiac hypertrophy and fibrosis." (PMID 38072986, 2023).
dilated cardiomyopathy (1 paper, 2023). Cardiomyopathy which is characterized by dilation and contractile dysfunction of the left and right ventricles. "To identify the molecular mechanism of dilated cardiomyopathy-related phenotypes in COX6A2 knockout cardiomyocytes, we used RNA-Seq technology to detect and analyze changes in the gene expression profiles of the two cardiomyocyte groups." (PMID 38072986, 2023).
esophageal cancer (1 paper, 2024). A primary or metastatic malignant neoplasm involving the esophagus. "Moreover, there is only one paper on COX6A2 and cancer prognosis, which demonstrated that COX6A2 is a prognostic protective gene in esophageal cancer." (PMID 38506898, 2024).
melanoma (1 paper, 2024). A malignant, usually aggressive tumor composed of atypical, neoplastic melanocytes. "MITFA and SOX10 have previously been identified as specific markers of malignant zebrafish melanomas in the original study, while PAICS and COX6A2 are newly discovered by our study, which actually play important biological roles and molecular functions in tumor development." (PMID 39494219, 2024).
parasitic infections (1 paper, 2023). "Although ivermectin is primarily used for treating parasitic infections, it has been identified as a mitochondrial ATP protector in CMs, enhancing mitochondrial ATP production in HL-1 CMs by upregulating the transcription of Cox6a2, a subunit of the mitochondrial respiratory chain." (PMID 37705046, 2023).
type 2 diabetes (1 paper, 2024). "Notably, overexpression of COX6A2 facilitated β-cell apoptosis, whereas its deficiency attenuated this process and ameliorates type 2 diabetes, suggesting a pro-apoptotic role of COX6A2 in β-cells." (PMID 39702527, 2024). "These insights reveal a novel regulatory mechanism for β-cell apoptosis and highlight COX6A2 as a possible therapeutic target for type 2 diabetes." (PMID 39702527, 2024).
tumor (4 papers, 2019 to 2024). "The combined analysis revealed sex, race, TMB, neoplasm histologic grade, Child–Pugh grade, MMRN1, OXT and COX6A2 transcription as independent risk factors." (PMID 36153509, 2022). "In univariate analysis, clinical characteristics (gender, age, T, N, M and tumor stage), APOA2, COX6A2, HIST1H1E, UBE2C, ERO1B and eight gene comprehensive risk scores were prognostic risk factors for patients with the EC (P < 0.05)." (PMID 35568702, 2022). "Sex, race, TMB, neoplasm histologic grade, Child–Pugh grade, MMRN1, OXT and COX6A2 transcription have been identified as independent risk factors." (PMID 36153509, 2022). "In addition, through differential expression analysis on the cell types that predominantly occupy the tumor and muscle regions based on the deconvolution of eMCI, some key genes with spatial heterogeneity of spatial expression patterns were detected, such as PAICS, MITFA, SOX10, and COX6A2." (PMID 39494219, 2024).
cardiovascular disease (1 paper, 2020). "In this pathway, upregulation of COX7B, COX17, and ATP6V1G3 as well as downregulation of COX6A2 and UQCRQ may lead to CKD complications with cardiovascular disease." (PMID 33247215, 2020).
COX6A2 also shares sentences with these, for which no sentence is quoted: Obesity (4 papers); cancer (2); cognitive deficits (2); Glucose intolerance (2); acute lymphoblastic leukemia (1); Alzheimer disease (1); Bradycardia (1); central nervous system disorder (1); energy metabolism disorders (1); hepatocellular carcinoma (1); Huntington disease (1); hyperglycaemia (1); hypertrophy (1); infection (1); metabolic disorders (1); non-alcoholic fatty liver disease (1); polyp (1).